TXNDC5 (thioredoxin domain containing 5)
Diseases named in the same sentence as TXNDC5 in open-access papers (continued):
Sharing a sentence is not in itself a finding about the gene and the disease.
Hepatic steatosis (1 paper, 2022). Steatosis is a term used to denote lipid accumulation within hepatocytes. "In this manuscript, we developed Txndc5-deficient mice using CRISPR-Cas9 technology and performed a liver RNA-seq to characterize and elucidate if any of the hepatic steatosis factors may be linked with this PDI." (PMID 35327511, 2022). "TXNDC5, as we hypothesized, was correlated with hepatic steatosis and redox control in the liver, showing an increased liver mass with a higher fat content linked to Saa1 and Saa2 expressions." (PMID 35327511, 2022). "All the findings may suggest an important role for TXNDC5 in hepatic steatosis development." (PMID 35327511, 2022).
Inguinal hernia (1 paper, 2020). Protrusion of the contents of the abdominal cavity through the inguinal canal. "We found variants at nine loci to associate with POP; five of which associate at genome-wide significance with POP, three that were previously associated with height (P < 1.4 × 10−5) at TXNDC5 (6p24.3), SLC12A2 (5q23.3) and LOXL1 (15q24.1) and one at WT1 that associates with inguinal hernia (11p13)." (PMID 32184442, 2020).
laryngeal squamous cell carcinoma (1 paper, 2024). A squamous cell carcinoma that arises from the larynx. "Cetuximab could diminish TXNDC5 expression, thereby augmenting the generation of ROS and developing the endoplasmic reticulum stress-related apoptosis of laryngeal squamous cell carcinoma cells." (PMID 39275334, 2024).
mesenchymal tumors (1 paper, 2022). "Among all the histological subtypes, TXNDC5 levels were highest in the mesenchymal tumors." (PMID 36106447, 2022).
metabolic syndrome (1 paper, 2024). A cluster of metabolic risk factors for CARDIOVASCULAR DISEASES and TYPE 2 DIABETES MELLITUS. "The roles of TXNDC5 in these pathways are gaining attention due to their implications in a range of disorders, from metabolic syndromes to neurodegenerative diseases." (PMID 38666927, 2024).
myocardial disease (1 paper, 2019). "Moreover, dysregulation of HERG1 or TXNDC5 may contribute to myocardial disease." (PMID 31331361, 2019).
nephritis (1 paper, 2015). Inflammation of renal tissue. "This more liberal view revealed FOS and LINC00339 (induction linked to nephritis), as well as MZB1 and TXNDC5 (induced in Type B patient samples), as increased in patients under steroid treatment." (PMID 26544975, 2015).
ovarian carcinoma (1 paper, 2024). A malignant neoplasm originating from the surface ovarian epithelium. "Auranofin (AF) as an anti-inflammatory and anti-cancer drug, upregulated TXNDC5 expression and protein oxidation in ovarian cancer cells where TXNDC5 upregulation compensated for the deficiency of PDI activity in the ER." (PMID 38666927, 2024). "Furthermore, suppression of TXNDC5 increased the sensitivity to carboplatin as a chemotherapy medication, highlighting its potential importance in carboplatin-resistant ovarian cancer cell lines." (PMID 38666927, 2024).
parasitemia (1 paper, 2025). "Though TXNDC5 was up-regulated in the B. bigemina attenuated-strain-inoculated group, parasitemia was barely perceptible." (PMID 39859202, 2025).
psoriasis (1 paper, 2024). An autoimmune condition characterized by red, well-delineated plaques with silvery scales that are usually on the extensor surfaces and scalp. "Researchers from the Yonsei University College of Medicine have found such biomarkers as psoriasis-associated fatty acid-binding protein (FABP5), moesin, and Rho-GDP dissociation inhibitor (RhoGDI), thioredoxin domain-containing protein 5 (TXNDC5), Ras suppressor protein-1 (RSU1) and vimentin." (PMID 39493718, 2024).
renal cell adenocarcinoma (1 paper, 2022). A carcinoma arising from the renal parenchyma. "NR4A1 has also been found to regulate the TXNDC5 gene in renal cell adenocarcinoma." (PMID 35934705, 2022).
Shock (1 paper, 2024). The state in which profound and widespread reduction of effective tissue perfusion leads first to reversible, and then if prolonged, to irreversible cellular injury. "TXNDC5 is upregulated in patients with septic shock compared to septic patients without shock or healthy controls; this suggests that inhibiting TXNDC5 can attenuate lipopolysaccharide-induced septic shock by inhibiting the NF-κB signaling pathway." (PMID 38666927, 2024).
steatosis (1 paper, 2023). Increased lipid within the cytoplasm of cells. "Moreover, hepatic fat influences TXNDC5, which has been linked to the regulation of ER stress, and may be crucial for the control of apolipoprotein B (APOB) and the development of steatosis." (PMID 38138960, 2023).
Testicular torsion (1 paper, 2025). Testicular torsion is when the spermatic cord to a testicle twists, cutting off the blood supply. "With the apparent restoration of testicular structure and spermatogenesis, our study provides a potential therapeutic strategy by targeting TXNDC5 in testicular torsion patients to reduce ischemia/reperfusion-induced testicular fibrosis and to restore their fertility." (PMID 40261983, 2025).
type 2 diabetes (1 paper, 2024). "On the other side, casein as a dietary protein source for type 2 diabetes, can downregulate TXNDC5." (PMID 38666927, 2024).
cancer (31 papers, 2014 to 2025). A tumor composed of atypical neoplastic, often pleomorphic cells that invade other tissues. "In brief, TXNDC5 is a promising prognostic marker for cancer progression, a therapeutic target and a molecular diagnostic indicator for cancer pathogenesis." (PMID 38629066, 2024). "In CRPC, TXNDC5 promotes cancer cell proliferation by causing cell cycle disorders between G2/M and S phases in vivo and in vitro." (PMID 35934705, 2022). "A second NR4A1-regulated pathway in cancer cells is associated with regulation of genes such as TXNDC5 and IDH1 that maintain high levels of redox equivalents and decrease intracellular stress." (PMID 26035713, 2015). "TXNDC5 can be used as a diagnostic marker and a therapeutic target in cancer." (PMID 38629066, 2024). "Several TXNDC5 polymorphisms have been associated with cancer." (PMID 25526565, 2014). "Furthermore, TXNDC5 could potentially serve as a diagnostic marker for certain types of cancer, aiding in early detection and personalized treatment approaches." (PMID 38666927, 2024). "TXNDC5 may be used as a diagnostic marker for a variety of cancers." (PMID 35934705, 2022). "TXNDC5 is highly expressed in endothelial cells (ECs), fibroblasts, pancreatic β-cells, liver cells, and hypoxic tissues, such as cancer endothelial cells and atherosclerotic plaques." (PMID 38666927, 2024). "In this review, we focus on the role of TXNDC5 in various diseases and discuss possible TXNDC5 applications for “TXNDC5-related diseases” particularly cancer, rheumatoid and fibrotic diseases." (PMID 38629066, 2024). "In conclusion, the insights have the potential to open new avenues in cancer treatment by targeting TXNDC5 to control aberrant inflammatory responses." (PMID 38629066, 2024). "Increased TXNDC5 expression can mediate neovascularization and promote cancer cell proliferation, invasion and metastasis." (PMID 38629066, 2024). "Overall, these results indicate that TXNDC5 is affected by different regulators in various cancers and that TXNDC5 plays an important role in promoting cancer proliferation, invasion and metastasis." (PMID 38629066, 2024). "In summary, TXNDC5 is a typical cancer-enhancing gene that is highly expressed and overexpressed in tumor tissues of several cancers and plays an important role in the development of cancer." (PMID 38629066, 2024). "Decrease the expression of TXNDC5 in cancer tissues can attenuate cell viability, inhibit cell colony formation, induce cell cycle arrest and apoptosis." (PMID 38629066, 2024). "In CRC and NSCLC, TXNDC5 is highly expressed in the early stages of cancer, so TXNDC5 can be used as a means to diagnose early cancer." (PMID 38629066, 2024). "TXNDC5 is highly expressed in endothelial cells, fibroblasts, pancreatic β-cells, liver cells, and hypoxic tissues, such as cancer endothelial cells and atherosclerotic plaques." (PMID 38666927, 2024). "Several studies found that TXNDC5 showed significantly increased expression in a variety of cancer tissues." (PMID 38629066, 2024). "It has been concluded that in cancer, TXNDC5 acts as a foe and responds to metabolic and cellular stress signals to promote the survival of tumor cells against apoptosis." (PMID 38666927, 2024). "The presence of TXNDC5 in metastatic renal cell carcinoma promotes cell growth, migration, invasion and increases resistance of cancer cells to chemotherapeutic agents." (PMID 38629066, 2024). "In summary, TXNDC5 has different oncogenic mechanisms in different cancers, and the complex mechanisms of TXNDC5 in cancer tissues deserve further exploration." (PMID 38629066, 2024). "Induced expression of TXNDC5 has been observed in a number of cancers, including of the cervix, colon, stomach, prostate, liver, and lung." (PMID 38138960, 2023). "Evidence obtained by immunohistochemical staining and Western blot showed that TXNDC5 expression was altered in a variety of cancers." (PMID 35934705, 2022).
cancer (continued). "In this paper, we summarize the structural and functional characteristics of TXNDC5 and its role in cancer, RA and other diseases." (PMID 35934705, 2022). "Recently update on SRSF10 and TXNDC5 have indicated their diverse and signaling regulatory roles in cancers." (PMID 35296659, 2022). "Moreover, TXNDC5 is known to play an important role in inflammation and controlling redox status, its absence made cells are more susceptible to apoptosis in several tissues, and its expression has been correlated with bad prognosis in multiple types of cancer since it provides more ROS tolerance." (PMID 35327511, 2022). "Among these genes, TXNDC5 is known to play a pro‐survival function under stress conditions which prompted us to investigate it further in cancer context." (PMID 36106447, 2022). "This article reviews the structure and function of TXNDC5 as well as its role and mechanism in cancer, RA and other diseases." (PMID 35934705, 2022). "Further analysis showed that all of these dysregulated proteins had cancer-related associations, such as PDIA5, DEF6, MZB1, TXNDC5, YARS2, MGST1, and PIH1D1." (PMID 35958927, 2022). "TXNDC5 is mainly expressed in liver and endothelial cells, although increased TXNDC5 levels have been reported in diseases in which oxygen is limited, including different types of cancer." (PMID 30200585, 2018). "It has been shown that NR4A1 maintains low levels of stress in cancer cells by regulating expression of TXNDC5 and IDH1 that in turn maintain high levels of cellular reducing agents." (PMID 26035713, 2015). "It has been reported that the expression of the TXNDC5 gene is upregulated in a number of carcinoma tissues compared with normal tissues." (PMID 25663872, 2015). "TXNDC5 can be exercised as a therapeutic target for cancers." (PMID 39275334, 2024). "Aberrant overexpression of TXNDC5 plays an important role in brain tissue and cancer progression." (PMID 38666927, 2024). "Investigating the regulatory mechanisms of TXNDC5 in cancer pathways may lead to the development of targeted interventions for cancer management." (PMID 38666927, 2024). "In conclusion, TXNDC5 plays an essential role in cancer diagnosis and therapy." (PMID 38629066, 2024). "TXNDC5 also influenced by other factors that promote the development of cancer." (PMID 38629066, 2024). "TXNDC5 plays an important role in cell physiologic processes, including oxidative stress, cell aging and a wide range of pathologies, such as rheumatoid arthritis, vitiligo, viral infections, diabetes, neurodegenerative disease and cancer." (PMID 29207620, 2017). "The Human Cancer PathwayFinder PCR Array, the Signal Transduction PCR Array and the Angiogenesis PCR Array were used to identify key novel molecules that regulate the tumorigenic process mediated by TXNDC5 expression in HeLa cells." (PMID 29207620, 2017). "A previous study indicated that the TXNDC5 gene may affect certain biological characteristics of cancer cells, promoting the growth and proliferation of tumor cells, or preventing their apoptosis." (PMID 25663872, 2015). "Thioredoxin domain-containing 5 (TXNDC5) is overexpressed in a number of human carcinomas." (PMID 25663872, 2015). "For instance, dysregulation in TXNDC5 may affect the cell cycle, through the cycling CDK5, histones or transcription factors such as ATF2 or ZNHIT2, being a possible cause of cancer." (PMID 25526565, 2014). "Due to the anaerobic metabolism of cancer cells, it has been stated that their proliferation could be due to hypoxia and this would induce TXNDC5." (PMID 25526565, 2014). "We observed that three disulfide isomerases, AGR2, AGR3, and TXNDC5, are overexpressed in cancer." (PMID 25243088, 2014). "Additionally, TXNDC5 promotes cancer progression by regulating various inflammatory factors." (PMID 38629066, 2024).
cancer (continued). "Finally, it has been concluded that in cancer, TXNDC5 acts as a foe, responding to metabolic and cellular stress cues to promote tumor cell survival against apoptosis, whereas in normal cells, TXNDC5 acts as a friend, protecting cells against oxidative and endoplasmic reticulum stress." (PMID 38666927, 2024). "This responsiveness to cellular stress cues may explain why TXNDC5 levels vary in specific cancers." (PMID 38666927, 2024). "Also, numerous studies link TXNDC5’s high expression with cancer, and there may be a possible connection between that and HSPA9." (PMID 38138960, 2023). "In addition to cancers and RA, the SNPs of TXNDC5 are also related to many other diseases." (PMID 35934705, 2022). "In addition, it has been reported that TXNDC5 is up-regulated in several cancers." (PMID 32769093, 2020). "Mmu-miR-505-5p was downregulated in Sca-1+CD31− compared to Sca-1+CD31+ cells, with targets Cyp1b1, Dcbld2, Igf1, and Ppp1r14b,Txndc5 increased in expression; Igf1 was involved in mTOR and PI3K-Akt signaling and Cyp1b1by with microRNAs in cancer." (PMID 27298624, 2016). "NR4A1 also regulates expression of genes such as thioredoxin domain containing 5 (TXNDC5) and isocitrate dehydrogenase 1 (IDH1) to maintain low oxidative stress in cancer cells." (PMID 26035713, 2015). "Next, we evaluated whether TXNDC5 plays a critical role on the anti-cancer effect in drug combinations; the DLD-1 cells were transfected with an empty vector or TXNDC5 vector, and then we evaluated the expression of TXNDC5 by Western blot." (PMID 39275334, 2024). "In contrast, the expression levels of TXNDC5, CD38, GAS6, FKBP2 and SDC1 were increased in the late stage of LUAD progression, indicating potential distinct roles in the occurrence and progression of the cancer." (PMID 37728413, 2023). "Currently there is no treatment targeting TXNDC5 or other oxidoreductases in cancer therapy thus further studies are warranted." (PMID 36106447, 2022). "The PI3K/AKT signaling pathway is involved in tumor progression in various types of cancer, including ESCC; however, its relationship with HERG1 and TXNDC5 remains unclear." (PMID 31331361, 2019). "Among these proteins, six are reportedly related to cell survival and death; i.e., RhoGDI, GRP78, TXNDC5, COMD9, EIF4E, and PRDX3, which reportedly affect Rho GTPase activity, ER stress, cancer progression, NF-κB suppression, cell growth, cell cycle progression, and apoptosis." (PMID 27428937, 2016). "Thioredoxin domain-containing 5 (TXNDC5) has three thioredoxin-like domains, is a member of the nineteen existing protein disulfide isomerase (PDI) families of oxidoreductases, is predominantly expressed in the ER, and plays a critical role in signal transduction and cancer development." (PMID 38138960, 2023). "Moreover, knockdown of NR4A1 or TXNDC5 by RNA interference also induced ROS in cancer cell lines suggesting that some ROS-inducing anticancer agents may also be NR4A1 ligands and that their anticancer activities may due, in part, to their activity as inverse NR4A1 agonists in cancer cells." (PMID 37808182, 2023).